TFEB (transcription factor EB)
Diseases named in the same sentence as TFEB in open-access papers (continued):
Sharing a sentence is not in itself a finding about the gene and the disease.
tauopathy (20 papers, 2014 to 2025). Neurodegenerative disorders involving deposition of abnormal tau protein isoforms (tau proteins) in neurons and glial cells in the brain. "Upon internalisation into astrocytes, astroglial TFEB promotes Tau degradation and inhibit its transmission in tauopathies." (PMID 40395993, 2025). "The TFEB signalling maintains lysosomal homoeostasis in microglia and plays a critical role in tauopathy of AD." (PMID 40395993, 2025). "Studies in another tauopathy model using rTg4510 tau transgenic mouse have also shown that TFEB expression enhanced lysosomal activity and clearance of autophagic substrates and phosphorylated tau." (PMID 40065324, 2025). "In accord with these findings, upregulation of TFEB in tauopathy mouse models leads to a marked reduction in soluble phosphorylated Tau and insoluble Tau aggregates, mitigating cognitive impairment." (PMID 40395993, 2025). "For instance, the delivery of the TFEB gene has been able to reduce pathological Tau levels and mitigate cognitive dysfunction in tauopathy models." (PMID 40395993, 2025). "In support of this view, accumulating evidence suggests that promoting autophagy through TFEB activation enhances clearance of phosphorylated tau and rescues neurotoxicity in mouse models of tauopathy." (PMID 39009859, 2024). "For tau pathology, TFEB overexpression in the brain of a rTg4510 mouse model of tauopathy dramatically reduces tau pathology, synaptic deficits, neurodegeneration and animal behavioral deficits." (PMID 36184826, 2023). "In a mouse model of tauopathy, the adenovirus-mediated overexpression of TFEB drastically reduces the levels of the disease marker phospho-Tau 16 weeks post-injection." (PMID 35665902, 2022). "Another study reported decreased levels of tau aggregates in the hippocampus and cortex upon neuron-targeted TFEB overexpression, together with attenuated learning and memory skill deficits, in a different mouse model of tauopathy." (PMID 35665902, 2022). "It has been shown that overexpression of TFEB in mouse models of tauopathy (PS19 and rTg4510) activates the lysosomal pathways, leading to reduced tau aggregation and lipofuscin granules and restored synaptic function." (PMID 36494352, 2022). "In a study involving a P301S tauopathy mouse model, neuron-targeted TFEB overexpression in the significantly reduced toxic p-Tau and lipofuscin levels in the cortex and hippocampus region with significantly improved cognitive features." (PMID 34970114, 2021). "Here we optimized an optical induction system based on EL222- light-responsive bacterial transcription factor to drive TFEB expression in different cell-based models of tauopathy." (PMID 32208437, 2020). "Taken together, for the first time, these results suggest that light-induced, optogenetic-based expression of TFEB can reduce p-Tau in a human relevant iPSN tauopathy model." (PMID 32208437, 2020). "Using an adenovirus vector expressing TFEB under the GFAP astroglial promoter, two tauopathy mouse models were tested for the effect of astrocytic TFEB upregulation." (PMID 32708198, 2020). "According to previous studies, TFEB overexpression is not only effective on attenuating tauopathy but can also attenuate amyloid pathogenesis by reducing APP and Aβ." (PMID 31858697, 2020). "Upon internalization into astrocytes, astroglial transcription factor – EB (TFEB, a master regular of autophagy) promotes tau degradation and the inhibition of tau transmission in tauopathies." (PMID 33177989, 2020). "More importantly, flag-TFEB expression remarkably reduced the levels of paired-helical filament (PHF)-tau from 372% in the P301S model of tauopathy to 171% (p < 0.001) in the cortex, and from 436% to 212% (p < 0.001) in the hippocampus." (PMID 27257626, 2016). "TFEB overexpression or its activation through small molecules or through synaptic stimulation, enhances clearance of hyperphosphorylated and misfolded tau, providing protection in mouse models of tauopathy." (PMID 39009859, 2024).
tauopathy (continued). "Similarly, neuron‐specific TFEB overexpression significantly reduces the expression of toxic p‐tau and the number of lipofuscin puncta in the cortex and hippocampus of P301S tauopathy mice, and attenuates the learning and memory deficits in mice." (PMID 36184826, 2023). "Overexpression of transcription factor EB (TFEB, a regulator of lysosomal biogenesis) in astrocytes promotes tau fibril species uptake and lysosomal activity as well as attenuates tau spreading and pathology in the hippocampus of P301S tauopathy mice." (PMID 37452321, 2023). "Here, we investigated whether a small molecule TFEB activator C1 discovered by us could be as effective as TFEB overexpression in attenuating tauopathy by using homozygous P301S Tau mice developed by Michael Goedert." (PMID 31858697, 2020). "In our study, when comparing the results from the P301S Tau mice and 5xFAD mice, C1 has stronger effects on attenuating tauopathy that APP turnover, indicating TFEB activation induced by C1 may primarily act on tauopathy." (PMID 31858697, 2020). "Accumulating evidence has demonstrated that TFEB can attenuate protein aggregates in cell and mouse models of AD and other tauopathies, resulting in alleviation of neurodegeneration and improvement of behavioral deficits, as well as the recovery of cognitive impairment." (PMID 33292395, 2020). "In the absence of disease-modifying therapy, a small-molecule activator of TFEB is therefore expected to have therapeutic potential for the treatment of AD, other tauopathies, as well as several other neurological disorders characterized by the accumulation of protein aggregates." (PMID 27257626, 2016). "Thus, the TFEB overexpression strategy is likely to have therapeutic potential for tauopathies, including AD, which are characterized by the deposition of protein aggregates partly due to impaired autophagy." (PMID 27257626, 2016). "Importantly, TFEB overexpression in the P301S model of tauopathy significantly reduced the levels of PHF-tau in the frontal cortex and CA1 region of the hippocampus, which in turn restored neuronal and synaptic markers." (PMID 27257626, 2016). "Interestingly, TFEB expression in the P301S model of tauopathy markedly reduced paired-helical filament-tau levels, which led to significant restoration of synaptic and neuronal markers, as well as learning and memory deficits." (PMID 27257626, 2016). "Thus, the activation of TFEB in vivo has therapeutic potential not only for tauopathy but for several other neurodegenerative disorders characterized by protein aggregates due to defects in autophagy." (PMID 27257626, 2016). "However, the levels of PHF-tau were reduced from 372% in the P301S model of tauopathy to 171% (p < 0.001) when flag-TFEB was overexpressed in the P301S/flag-TFEB double-transgenic mice in the cortex at 7 months of age." (PMID 27257626, 2016). "In addition, TFEB overexpression rescues memory deficits in the P301S tauopathy mouse model." (PMID 35948663, 2022). "Since autophagy is the sole mechanism for the clearance and degradation of damaged organelles and misfolded proteins; and this is dysfunctional in AD and related tauopathies; we believe that TFEB, could ameliorate these pathological hallmarks of neurodegenerative diseases." (PMID 34970114, 2021). "Furthermore, since the T231 mutation causes a potent neurotoxic conformation called cis-p-Tau (or ‘Cistauosis’, as a result of phosphorylation of tau at T231), TFEB’s role in significantly reducing T231D/S235D levels supports the therapeutic potential of targeting TFEB against tauopathies." (PMID 32208437, 2020). "In addition, triggering the transcription factor EB (TFEB), a key regulator of lysosomal biogenesis, could enhance the autophagy-lysosomal pathway within astrocytes, resulting in the increased uptake and degradation of Aβ, thus also mitigating tauopathy." (PMID 39596378, 2024).
tauopathy (continued). "Together, we conclude that tauopathy astrocytes show signs of a JUN(B)-mediated pro-inflammatory state, while TAs in PSP additionally display a TFEB-mediated downregulation of lysosomal degradation." (PMID 35976433, 2022). "Third, and most importantly, TFEB overexpression reduces PHF-tau levels in the cortical and hippocampal brain regions of the P301S model of tauopathy." (PMID 27257626, 2016). "In addition, astroglial TFEB overexpression reduced tau pathology, spreading, and gliosis in the hippocampus of PS19 tauopathy mice." (PMID 40065324, 2025). "Previous studies have shown that TFEB overexpression can remarkably reduce the hyperphosphorylated and misfolded MAPT/Tau proteins, and rescue behavioral/learning deficits in rTg4510 and P301S mice models of tauopathy." (PMID 31858697, 2020). "Another important finding in the present study is the reduced levels of PHF-tau, but not of total tau, in the P301S mouse model of tauopathy due to TFEB overexpression-mediated autophagy." (PMID 27257626, 2016). "Thus, the activation of TFEB is a promising strategy to counter dysfunctional autophagy and increased PHF-tau pathology in AD and other tauopathies." (PMID 27257626, 2016). "Increased expression of TFEB in astrocytes in the PS19 tauopathy mouse model reduced tau pathology and decreased levels of astrocyte gliosis, although increased expression of astrocytic TFEB in a more rapidly progressive tauopathy mouse model did not reduce tau pathology." (PMID 34987360, 2021). "C1, an mTOR-independent activator of TFEB, efficiently reduces APP, APP C-terminal fragments (CTF-β/α), Aβ and Tau aggregates in three AD animal models, such as beta-amyloid precursor protein pathology (5xFAD mice), tauopathy (P301S mice) and the APP/Tau combined pathology (3xTg-AD mice)." (PMID 33292395, 2020). "Since hyperphosphorylated tau and synaptic pathology correlate with learning and memory deficits in the P301S model of tauopathy, and since TFEB overexpression significantly reduces PHF tau levels, we were interested to verify whether TFEB expression also has any impact on behavior." (PMID 27257626, 2016).
Cognitive impairment (15 papers, 2016 to 2026). Abnormal cognition is characterized by deficits in thinking, reasoning, or remembering. "Activation of peroxisome proliferators-activated receptors α (PPARα) by gemfibrozil and Wy14643 was demonstrated to enhance TFEB-mediated autophagy, resulting in reduced AD-associated pathologies and cognitive deficits." (PMID 37191408, 2023). "Meanwhile, the presence of the TFEB rs1062966T allele (CT + TT) was associated with a lower risk of cognitive impairment in comparison with the presence of the CC genotype (adjusted OR = 0.636, Bonferroni correction confidence interval = 0.405–0.998)." (PMID 34970136, 2021). "Subjects carrying the TFEB rs1062966T allele (CT + TT) showed a lower risk of cognitive impairment than the subjects with the CC genotype (dominant model: adjusted OR = 0.636, Bonferroni correction confidence interval = 0.405–0.998, P = 0.008)." (PMID 34970136, 2021). "In the co-dominant model, the risk of developing cognitive impairment was 1.553 times higher in carriers of the TFEB rs14063AG genotype than in carriers of the GG genotype (adjusted OR = 1.553, Bonferroni correction confidence interval = 1.007–2.397)." (PMID 34970136, 2021). "After Bonferroni correction and adjustment for age, gender, ethnicity, and education level as covariates, the association of TFEB rs1062966 and rs14063 SNPs with cognitive impairment was significant in the dominant model in the total population (P < 0.00833)." (PMID 34970136, 2021). "In the dominant model, subjects carrying the TFEB rs1062966T allele (CT + TT) showed a lower risk of cognitive impairment than those carrying the CC genotype (dominant model: adjusted OR = 0.543, Bonferroni correction confidence interval = 0.311–0.946, P = 0.004)." (PMID 34970136, 2021). "The risk of developing cognitive impairment was 1.547 times higher in those carrying the TFEB rs14063A allele (AG + AA) than in those with the GG genotype (dominant model: adjusted OR = 1.547, Bonferroni correction confidence interval = 1.021–2.345, P = 0.006)." (PMID 34970136, 2021). "In the co-dominant model, the presence of the TFEB rs1062966 CT genotype was more strongly associated with a reduced risk of cognitive impairment than the presence of the CC genotype (co-dominant model: adjusted OR = 0.510, Bonferroni correction confidence interval = 0.275–0.948, P = 0.004)." (PMID 34970136, 2021). "The association between TFEB gene polymorphisms and cognitive impairment observed in the present study indicates that polymorphisms at some SNP loci of the TFEB gene may affect TFEB gene expression and cognitive function." (PMID 34970136, 2021). "In the dominant model, subjects carrying the TFEB rs1062966T allele (CT + TT) had a lower risk of cognitive impairment than those carrying the CC genotype (dominant model: adjusted OR = 0.510, Bonferroni correction confidence interval = 0.281–0.928, P = 0.003)." (PMID 34970136, 2021). "Similarly, TFEB is associated with the autophagy-lysosomal pathway and may aid in reducing inflammation and cognitive impairment via the cannabinoid receptor type II." (PMID 37258616, 2023). "The haplotype analysis suggested that the rs14063A–rs1062966C–rs2278068C–rs1015149T haplotype of the TFEB gene increased the risk of cognitive impairment (P < 0.05) and that the rs14063G–rs1062966T–rs2278068C–rs1015149C haplotype was associated with a reduced risk of cognitive impairment (P < 0.05)." (PMID 34970136, 2021). "Targeted TFEB activation in microglia reprograms degradative and immune pathways, enhancing Aβ clearance while alleviating neuroinflammation and cognitive impairment in AD." (PMID 41673711, 2026). "Genetically downregulating ROCK1 lowered its interference with TFEB, promoted TFEB nuclear distribution, lysosomal biogenesis and lysosome-mediated Aβ clearance, and eventually prevented pathological traits and cognitive deficits in APP/PS1 mice." (PMID 39497162, 2024).
Cognitive impairment (continued). "Recently, a study showed that celastrol reduces phosphorylated Tau aggregates and attenuates cognitive deficits in P301S Tau and 3xTg mice by enhancing TFEB‐mediated autophagy and lysosomal biogenesis." (PMID 36184826, 2023). "Chlorogenic acid (CGA), a phenolic acid isolated from fruits and vegetables, restores autophagic flux in the brain and alleviates cognitive impairment in APP/PS1 mice by activating the mTOR/TFEB signaling pathway." (PMID 36184826, 2023). "Genotypic and allelic frequencies of TFEB SNPs in the control and cognitive impairment groups [n (%)]." (PMID 34970136, 2021). "ESC‐sEVs treatment ameliorates H‐NSCs senescence by inhibiting mTORC1 activation, and promoting TFEB nuclear translocation and lysosome resumption, thereby reversing senescence‐related neurogenesis dysfunction and cognitive impairment in VD." (PMID 32440476, 2020). "Another important finding in the present study is the marked attenuation of cognitive deficits seen in the P301S mice when TFEB was overexpressed." (PMID 27257626, 2016). "Genetic or pharmacological inactivation of GSK3β promotes the nuclear accumulation of TFEB to induce lysosomal biogenesis and autophagy, leading to a reduction in Aβ1-42 and phosphorylated tau levels and subsequent amelioration of cognitive deficits in AD murine models." (PMID 37191408, 2023). "In addition, chlorogenic acid treatment can protect Aβ-induced injury in SH-SY5Y neurons and alleviate cognitive impairments in AD transgenic mice via enhancing the activation of the mTOR/TFEB signaling pathway." (PMID 35214904, 2022). "Moreover, ESC-exosomes treatment also alleviated hippocampal neural stem cells senescence and neuron differentiation capacity, and reversed cognitive impairment by inhibiting mTORC1 activation, thereby promoting TFEB nuclear translocation and lysosome resumption." (PMID 35851059, 2022). "One limitation is that we did not observe whether inhibition of TFEB expression or inhibition of TFEB nuclear translocation could counteract the cognitive impairment caused by sleep deprivation, and the expression changes of autophagy‐related genes by TFEB, except for p62, were not examined." (PMID 37485782, 2024). "Since these Braak stages are also accompanied by mild cognitive impairment (MCI), reduction in TFEB protein levels is correlated with the MCI." (PMID 27433468, 2016).
lung cancer (15 papers, 2018 to 2025). A malignant neoplasm involving the lung. "The degradation of MAP4K3 triggers transcription factor EB (TFEB)-dependent autophagy, causing arrest in lung cancer cell proliferation and effectively inhibiting tumor growth." (PMID 38628670, 2024). "β-ELE, a compound under investigation for its anti lung cancer properties in clinical settings across China, demonstrates a binding affinity to TFEB, a master regulator of lysosome biogenesis." (PMID 39104501, 2024). "For example, in a mouse model of lung cancer with liver metastasis, TFEB augmented the metastasis by increasing autophagy through upregulating cathepsins secretion and lysosome synthesis." (PMID 34490237, 2021). "TMEM106B modulates the expression of the CLEAR network lysosomal genes in lung cancer cells in a TFEB-dependent manner, and drives lung cancer metastasis." (PMID 33292395, 2020). "Given that, inhibition of TFEB by gene silencing or drugs can markedly enhance the sensitivity of tumor cells to chemotherapy among glioblastoma, lung cancer, pancreatic cancer, and ovarian cancer through either impairing autophagy flux or inducing mitochondrial apoptosis." (PMID 34490237, 2021). "In addition, increased TFEB expression was noticed in both glioblastoma and lung cancer developing resistance to chemotherapy." (PMID 34490237, 2021). "It was found that the inhibition of PLK4 in TFEB and TFE3 double-knockout cells drastically reduced the proliferation of lung cancer cells, providing a rationale for combination therapies." (PMID 41488365, 2025). "Since TMEM106B has been shown to regulate TFEB activity in neuronal cells, we wanted to determine whether TMEM106B similarly regulates TFEB in a manner that is required for TMEM106B-driven phenotypic changes in lung cancer cells." (PMID 30013069, 2018). "In a TFEB-dependent manner, TMEM106B could modulate the expression of lysosomal genes of the coordinated lysosomal expression and regulation (CLEAR) pathway in lung cancer cells and patient samples." (PMID 30013069, 2018). "In an in vivo setting, β-ELE demonstrates significant tumor growth inhibition, an effect compromised in the absence of TFEB, reinforcing the crucial role of TFEB in mediating β-ELE-induced anticancer responses in lung cancer." (PMID 39104501, 2024).